HPSE (heparanase)
Diseases named in the same sentence as HPSE in open-access papers (continued):
Sharing a sentence is not in itself a finding about the gene and the disease.
tumor (continued). "In addition, higher levels of vascular endothelial growth factor (VEGF) and hepatocyte growth factor (HGF) in exosomes derived from heparanase high expressing cells are in comparison with heparanase low expressing cells, and better mediate spreading of tumour cells and invasion of endothelial cells." (PMID 35454762, 2022). "This could indicate that heparanase is exerting a proinflammatory role, which could mean that non-tumor adjacent tissue also presented an increase in its inflammatory status that could be the basis for future tumor initiation." (PMID 36139645, 2022). "Similarly, circHIPK3 could target miR-558 for sponging to inhibit the expression of heparanase (HPSE) and suppress the migration, invasion, and angiogenesis of tumor cells." (PMID 34824999, 2021). "This suggests that in PTC, heparanase and Hpa2 may co-operate in driving tumor metastasis." (PMID 33959505, 2021). "Notably, MMPs and heparanase induction by HDACi may functionally result in alteration of the extracellular matrix structure and a tumor microenvironment permissive for cell invasion." (PMID 34857011, 2021). "Therefore, knockdown of heparanase expression in the tumor microenvironment may control the growth of tumor cells and even prolong the survival of the cancer patients." (PMID 34220326, 2021). "Moreover, heparanase drives exosome biogenesis and regulates exosome function, thereby controlling cell behaviors both locally within the tumor microenvironment and at sites distal to the tumor." (PMID 32899927, 2020). "The presence of heparanase in the nucleus leads to loss of the heparan sulfate proteoglycan syndecan-1 from the nucleus, resulting in enhanced histone acetyltransferase (HAT) activity and upregulation of expression of VEGF and MMP9, two genes that contribute to an aggressive tumor phenotype." (PMID 32899927, 2020). "Heparanase is an important player not only in maintaining homeostasis, as a postsynthetic modification enzyme for HS structure but also for its non-enzymatic and HS-independent effects which may contribute to tumor aggressiveness." (PMID 31963505, 2020). "Extracellularly heparanase is one of an array of enzymes that act on the extracellular matrix and basement membrane surrounding a primary tumor to weaken these structures and so facilitate tumor cell invasion into the surrounding tissues and assist metastasis formation." (PMID 31850210, 2019). "However, since these patients had higher instances of metastasis, it suggests that these lymphocytes may be preparing to seek out tumor cells for clearance, given that heparanase is often upregulated upon T cell activation." (PMID 31110966, 2019). "In addition, exosomes may play a role in heparanase upregulation by carrying secreted heparan sulfate from tumor cells, thus suggesting a mechanism of crosstalk between tumor cells and circulating lymphocytes." (PMID 30922347, 2019). "The combined results explained the influence of the tumor microenvironment in carcinogenesis, which led to insight into the possible molecules, such as syndecan-1 and heparanase, which could be used as targets for tumor prognosis and as future supplementary treatment for cancer." (PMID 30922347, 2019). "In addition, administering heparanase peptide-pulsed DCs after injecting B16 tumor cells could slow tumor growth." (PMID 31110966, 2019). "Also overlooked is the fact that anti-heparanase drugs given systemically will act on the heparanase secreted by the host's tumor invading immune cells, and this could retard their immune-surveillance protective effects and so allow tumor growth." (PMID 31850210, 2019). "This activity is strongly implicated in tumour metastasis and angiogenesis, but HPSE might also affect cancer and coagulation in a non-enzymatic manner." (PMID 31327867, 2019). "Similarly, much is still unknown about how heparanase inhibitors affect the anti-tumor immune response, despite their current use in clinical trials against a range of cancers." (PMID 31110966, 2019).
tumor (continued). "In addition, there are examples where heparanase gene silencing has resulted in tumors that are less vascularised and less metastatic than their controls, all of which very strongly point a contribution of heparanase in tumor angiogenesis." (PMID 31850210, 2019). "Heparanase activity digests HSPGs, resulting in increased endothelial permeability that enables the passage of invading cells through established boundaries, and the release of sequestered growth factors and soluble HS fragments that support angiogenesis and tumor growth." (PMID 32010611, 2019). "Functional evaluation demonstrated that these KLRG1+CD8 T cells could kill tumor cells in vitro and in vivo in Granzyme B- and Fas/FasL-dependent manners with no tumor antigen specificity, and tend to migrate into tumor sites by high expression of heparanase." (PMID 31664180, 2019). "Likewise, heparanase silencing reduces cellular invasion and tumor growth." (PMID 29721203, 2018). "Therefore, HPSE represents an attractive target for the development of broad spectrum drugs which may have antimicrobial, anti-inflammatory to anti-tumor activities." (PMID 30555321, 2018). "Also, equipping TRUCK T cells with the ability to secrete enzymes (such as heparanase) that ameliorate their infiltration to the tumor stroma can increase the number of infiltrated CAR T cells to the solid tumor site and thus can increase the anti-tumor efficacy of these cells." (PMID 30108584, 2018). "Moreover, heparanase expression and the degree of angiogenesis were reduced in tumor tissues." (PMID 28505136, 2017). "Taking into account the fact that degradation of ECM and BM comprises an initial and essential step for cancer cells to invade and metastasize, it is plausible that overexpression of heparanase may facilitate many aspects of tumor development, including migration, invasion and metastasis." (PMID 24632672, 2014). "Using RT-PCR and Western Blotting techniques, Chen and colleagues demonstrated that the expression of HPSE was significantly associated with TNM grade and invasion to nerves or lymph nodes although did not reveal a significant difference between histological differentiation and the tumor size." (PMID 25105093, 2014). "Furthermore, matrix degradation enzymes derived from the tumor itself or the tumor microenvironment, like heparanase and matrix metalloproteinases, ADAM as well as ADAMTS are involved in the cleavage of SDCs ectodomain at the HS and protein core level, respectively." (PMID 24551591, 2014). "Upon secretion of heparanase from metastatic tumour cells, the enzyme hydrolyses the glycosidic bonds of heparan sulfate chains attached to proteoglycans to a product of 10–20 sugar units in length, leading to penetration of the endothelial cells of blood vessels and target organs by the tumor cell." (PMID 25295847, 2014). "In patients undergoing hepatic resection, expression of heparanase mRNA was detected in 47% of HCCs and was significantly correlated with larger tumor size, presence of portal vein invasion, higher overall tumor invasiveness, and tumor microvessel density (MVD)." (PMID 25105093, 2014). "However, astrocytes may also contribute to the invasiveness of tumor cells in the brain by producing enzymes such as heparanase that degrade components of the extracellular matrix of the brain." (PMID 24133630, 2013).
tumor (continued). "Two reasons explain why heparanase is being seen as a universal tumor-associated antigen: heparanase is expressed in several types of advanced tumors, and dendritic cell expressing heparanase are able to elicit heparanase-specific cytotoxicity T lymphocytes (CTL) against tumor cells." (PMID 23984412, 2013). "Levels of heparanase expression in tumour cells correlate with their metastatic potential; elevated levels of heparanase mRNA and protein have been found in cancer patients who show significantly shorter postoperative survival times than patients whose heparanase levels are normal." (PMID 22719856, 2012). "Therefore, the excessive expression of HPSE therefore may accelerate tumor cell dissemination, enabling the penetration of cells through the ECM barrier and improving tumor cell adhesion to endothelial cells and the subendothelial ECM by cleaving HSPGs." (PMID 22719918, 2012). "Thus, heparanase may facilitate tumor cell invasion and neovascularization, both critical steps in tumor progression." (PMID 22363633, 2012). "For example, HPSE splice variant 6 from Spalax showed inhibition of HS degradation, suppression of tumor growth and no enzymic activity, while splice variant 7 could enhanced tumor growth but had no enzymatic activity." (PMID 22952874, 2012). "Heparanase is an endo-h-D-glucuronidase that has the ability to cleave the heparan sulfate chain of heparan sulfate proteoglycans, and facilitates the invasion and metastasis of tumor cells by deteriorating the basement membrane (BM) and extracellular matrix barriers." (PMID 22363633, 2012). "Thus, inhibition of heparanase enzymatic activity is expected to suppress tumor progression." (PMID 23908791, 2011). "Thus, strategies to enhance nuclear heparan sulfate levels may prove effective in blocking at least some of the heparanase-mediated effects that promote tumor growth and metastasis." (PMID 19305494, 2009). "The resulting changes in gene expression facilitated by the loss of nuclear syndecan-1 could explain how heparanase enhances expression of MMP-9, VEGF, tissue factor and perhaps other effectors that condition the tumor microenvironment to promote an aggressive cancer phenotype." (PMID 19305494, 2009). "This ability of heparanase to regulate nuclear syndecan-1 may represent a mechanism whereby heparanase influences gene transcription with downstream effects that promote the aggressive tumor phenotype." (PMID 19305494, 2009). "This increased rigidity limits the ability of CAR-T cells to penetrate the tumor, which can be limited by the enzymatic action of matrix metalloproteinases (MMP) and heparanase to degrade and reorganize dense networks." (PMID 40699720, 2025). "Heparanase inhibitors, such as defibrotide and pixatimod (PG545), have shown superior efficacy in inhibiting tumor progression, compared to cisplatin." (PMID 40904706, 2025). "One approach involves engineering CAR-Ms to express matrix-remodelling enzymes, such as hyaluronidase or heparanase, which facilitate the degradation of ECM components, thereby improving CAR-M infiltration into tumour tissue." (PMID 40624498, 2025). "Both heparanase-expressing CAR T-cells and hyaluronidase-expressing CAR T-cells have demonstrated increased tumor infiltration and enhanced anti-tumor activity, including when hyaluronidase and IL-7 armoring were combined." (PMID 41019052, 2025). "Engineering CAR-T cells to express heparanase (HPSE), an enzyme that degrades heparan sulphate proteoglycans in the ECM, has enhanced tumour penetration and improved therapeutic efficacy." (PMID 40624498, 2025). "Among its key functions, HPSE regulates oncogenes such as BRAF, c-Myc, and RAS, thereby promoting tumor development and progression." (PMID 41301515, 2025). "Another heparanase inhibitor, PG545 (pixatimod), has also shown promising results in inhibiting tumor growth and angiogenesis." (PMID 39594665, 2024).
tumor (continued). "In addition, heparanase (HPSE), an endoglycosidase that acts within the ECM to trim HS chains and generate specific short fragments by exposing the core protein for cleavage by MMPs, is largely involved in CD138 shedding and is severely implicated in tumor angiogenesis, growth and metastasis." (PMID 38655136, 2024). "Heparanase (HPSE-1) is an endoglycosidase that degrades ECM and basement membranes of the BBB to facilitate tumor progression and metastasis to the brain." (PMID 37190188, 2023). "With respect to mechanism, heparanase is involved in the proteolytic degradation of HSPGs at the BBB, leading to barrier disruption and ECM remodeling, which enhances tumor cell invasion of the brain." (PMID 37688612, 2023). "HPSE is the sole endoglycosidase able to cleave heparan sulfate (HS) chains, an important component of the ECM in the tumor microenvironment." (PMID 37233489, 2023). "We hypothesize that the overexpression of MMP14 might have certain advantages over the expression of secreted heparanase or the systemic application of lysyl oxidase inhibitors, as MMP14 is a membrane-anchored protein lowering the risk of structural changes outside of the tumor tissue." (PMID 37139603, 2023). "There is evidence that heparanase and SDC1 work together to promote diverse signaling pathways both in tumor cells and in surrounding microenvironmental cells, such as endothelial and immune cells." (PMID 36980680, 2023). "We previously demonstrated that increased heparanase (HPSE) expression in tumor cells enhances secretion and alters the composition of tumor‐released exosomes." (PMID 37091070, 2023). "Following the pattern observed in heparanase and MMP9 levels, vimentin showed a tendency to decrease in stage III when compared to stage II in tumor tissue." (PMID 36139645, 2022). "Mammalian heparanase (HPA) is the only endoglycosidase that degrades heparan sulfate, a vital element of the extracellular matrix (ECM) and tumor microenvironment." (PMID 35970822, 2022). "Equipping GD2 CAR T cells with heparanase led to improved CAR T cell infiltration and anti-tumor effect in several different in vivo xenograft models." (PMID 36366354, 2022). "The present study focuses on the development of related triazolo–thiadiazole compounds that inhibit heparanase enzymatic activity, ECM degradation, cell invasion, experimental metastasis, and tumor growth in mouse models." (PMID 34199150, 2021). "One group reported that overexpression of heparanase (HPSE) in CAR-T cells enhanced the abilities of the cells to degrade heparan sulfate proteoglycans and infiltrate tumor tissues." (PMID 34326835, 2021). "After further dividing patients into two subgroups based on multiple or single tumor foci (STF), we found that the MTF group had a higher expression level of HPSE than that in the STF group." (PMID 33597510, 2021). "For example, when heparanase cleaves HS from perlecan in the basement membrane it releases bound FGF2, which promotes angiogenesis, wound healing and tumour formation." (PMID 33450893, 2021). "Changes in tumor growth and immune phenotypes in response to molecules such as STAT3, KDM4A or heparanase already demonstrate unique responses that depend on their respective activities." (PMID 35069219, 2021). "The expressions of heparanase in 4T1 and B16F10 cells were significantly reduced in tumor cells after infection with Salmonella (MOI=200) (p<0.05 for S.C. MOI=0 versus MOI=200 in 4T1; p<0.01 for S.C. MOI=0 versus MOI=200 in B16F10)." (PMID 34220326, 2021). "Non-anticoagulant heparin derivatives such as SST0001 or roneparstat significantly downregulated heparanase-dependent cleavage of syndecan-1 HS chains, attenuated HGF, VEGF, and MMP-9 expression resulting in decreased tumor growth and angiogenesisinvivo." (PMID 33800172, 2021).
tumor (continued). "We also noted a profound reduction in VEGF levels in tumor sections derived from 4-MMI treated vs. untreated mice, likely due to inhibition of heparanase-mediated VEGF gene expression and/or release." (PMID 34199150, 2021). "Recently, the target range of heparin derivatives was extended to tumor-related proteins such as transforming growth factor-β1 (TGF-β1), CXCL12, vascular endothelial growth factor C (VEGF C), and heparanase." (PMID 34638867, 2021). "Heparanase (HPSE), an endoglycosidase that cleaves heparan sulfate, regulates a variety of biological processes that promote tumor progression." (PMID 34461608, 2021). "CAR-T cells that have been engineered to express heparanase, an enzyme that degrades HSPG, show enhanced tumor infiltration and antitumor activity." (PMID 33824268, 2021). "Here we found HPSE expression was up-regulated in HCC tissues and its over-expression was correlated with multiple tumor foci, microvascular invasion, and poor outcome of HCC patients." (PMID 33597510, 2021). "Here, we provided evidence of a positive cooperation between HDACi and the HS mimetic/heparanase inhibitor SST0001 in both in vitro and in vivo tumor models." (PMID 34857011, 2021). "HPSE expression was closely correlated with Edmondson’s classification (P = 0.0318), AJCC staging of HCC (8th edition) (P = 0.0375), multiple tumor foci (MTF) (P = 0.0093), and microvascular invasion (MVI) (P = 0.0043)." (PMID 33597510, 2021). "HPSE acts in concert with a number of oncogenes such as Ras, Myc and BRAF, which promotes tumour growth." (PMID 33256730, 2020). "Collectively, this study demonstrates that heparanase promotes chromatin opening and transcriptional activity, some of which likely is through its impact on diminishing PTEN tumor suppressor activity." (PMID 32899927, 2020). "All of these tumor-promoting effects of heparanase are opposed by HPSE2, which lacks the ability to degrade heparan sulfate and importantly has the ability to inhibit heparanase by competing with heparanase for heparan sulfate." (PMID 32175269, 2020). "Results showed that the expression levels of HPSE, HLA-F, and SELL were downregulated in most tumor tissues with high CDYL2b expression compared to the expression levels in matched normal breast tissues." (PMID 32373210, 2020). "Therefore, compared with KLRG1−CD8 T cells, higher expression of heparanase might contribute to the migration of KLRG1+CD8 T cells into tumor sites, where KLRG1+CD8 T cells could exert stronger cytotoxicity against tumor cells in FasL- and Granzyme B-dependent manners." (PMID 31664180, 2019). "This is likely a result of heparanase increasing ECM breakdown, as heparanase was shown to enable viral particles to penetrate deeper into tumor spheroids." (PMID 31110966, 2019). "In pancreatic cancer models, ionizing radiation was shown to upregulate heparanase by downregulating the transcription repressor EGR1, ultimately leading to the enhanced invasive capability of tumor cells." (PMID 30413079, 2018). "Heparanase overexpression enhances the phosphorylation of molecules in the ERK and AKT pathways to stimulate the proliferation and migration of tumor cells." (PMID 28505136, 2017). "The multi-epitope vaccines constructed by these epitopes were able to induce heparanase-specific CTLs to secrete IFN-γ and lyse tumor cells." (PMID 28509875, 2017). "In the ECM, heparan sulfates (HS) are cleaved by heparanase which induces, as a consequence, the release of numerous pro-angiogenic chemokines and growth factors, including VEGF and FGF-2, in the tumor microenvironment." (PMID 28486399, 2017). "The study of NAX014 implied that NAX014-dependent inhibition of heparanase could determine the lower vessel density and the reduced tumor vascularization could also be related to the decreased intratumoral immune infiltration, which may affect the anti-tumor activity." (PMID 28505136, 2017).